CSPG4 (chondroitin sulfate proteoglycan 4)
Diseases named in the same sentence as CSPG4 in open-access papers (continued):
Sharing a sentence is not in itself a finding about the gene and the disease.
tumor (continued). "CSPG4P12, as a highly homologous pseudogene of CSPG4, most likely possesses a similar biological role to CSPG4 which has been demonstrated to play an important role in tumor cell growth and metastasis." (PMID 38877481, 2024). "In GBM-NS models with low CSPG4 expression, microglial cells surrounding the tumor induced CSPG4 upregulation on the tumor cell surface by releasing TNF-α, thereby enhancing the therapeutic efficacy of CAR-T cells." (PMID 39506843, 2024). "Further research on CSPG4-mediated tumour formation in vivo and ex vivo in human tumour explants or 3D models, such as organoids, is still necessary." (PMID 39409881, 2024). "The number of nodules and the tumor burden of the omentum were significantly decreased in the sh-CSPG4 mouse models." (PMID 38338902, 2024). "Chondroitin sulfate proteoglycan-4 (CSPG-4) is another potential antigenic target in multiple tumor types." (PMID 37235419, 2023). "CSPG4 is a hyperglycosylated transmembrane protein with a low expression in normal tissues and hyperexpressed in several tumor types, including TNBC." (PMID 36900394, 2023). "Here we demonstrate that co-expression of a CCR can significantly enhance the anti-tumor response of CSPG4-CAR T cells in vitro as well as in vivo." (PMID 37901209, 2023). "A recent investigation elucidated CSPG4's role as a polymeric membrane proteoglycan, promoting tumor proliferation and metastasis through the tyrosine kinase pathway while also influencing tumor energy metabolism to facilitate neovascularization." (PMID 38015710, 2023). "With the primary goal to improve the safety of CSPG4-targeting CAR T cell therapies, we used a low-affinity antibody-derived CSPG4-CAR, which showed low cytotoxic activity, consequently entailing a minimized risk for on-target/off-tumor toxicity." (PMID 37901209, 2023). "The carriers of ofCS are syndecan 1 (SDC1) and chondroitin sulfate proteoglycan 4 (CSPG4), proteoglycans that are highly expressed in BC and thus increase the overall amount of ofCS in the tumor." (PMID 37110670, 2023). "CAR T therapy targeting CSPG4 in GBM neurospheres showed cytotoxic effects against tumor cells, induced IFN-γ and IL-2, and showed proliferation in the presence of tumor cells." (PMID 36900205, 2023). "Two days after tumor cell grafting, mice were treated with CSPG4-CAR.CIK every three days for a total of five times (3 × 106 cells/mouse each administration)." (PMID 37993874, 2023). "An experiment involving CSPG4-specific mAb 225.28 demonstrated the regression induction of tumor metastasis in a lung metastasis model." (PMID 37508851, 2023). "This again substantiates the need for simultaneous target antigen engagement through both CAR and CCR, which highly increases the safety and tumor cell restriction of CSPG4-targeted T cell therapy." (PMID 37901209, 2023). "CSPG4-specific monoclonal antibody (mAb) inhibited TNBC cell migration and growth, caused significant regression of lung metastasis, and limited tumor recurrence in a mouse immunodeficient in situ xenograft model." (PMID 37457288, 2023). "Univariate analysis demonstrated a correlation between patient prognosis and tumor stage (p = 0.023) as well as CSPG4 expression (p = 0.002)." (PMID 38015710, 2023). "Anti-CSPG4 antibodies designed with immune-activating features and able to restrict tumor growth are still required." (PMID 37185332, 2023). "This aspect of increasing tumor cell specificity is also highly relevant in the context of targeting CSPG4, due to its role in multiple physiological processes and the expression on healthy tissues." (PMID 37901209, 2023). "CSPG4 IgE treatment restricted tumor growth or improved survival across distinct in vivo models, irrespective of the tumor site, and with engraftment of immune cells from either healthy volunteers or patients." (PMID 37185332, 2023).
tumor (continued). "Data pertaining to immunohistochemistry of tissue microarrays revealed that CSPG4 exhibited significantly deeper staining in normal bladder tissue compared to tumor tissue, consistent with our prior analysis." (PMID 38015710, 2023). "CSPG4-CAR.CIK markedly delayed tumor growth to a significantly higher extent compared to unmodified CIK and untreated mice (p < 0.0001)." (PMID 37993874, 2023). "Preclinical data support the possibility to exploit a therapeutic frame based on the higher expression levels of CSPG4 on tumor cells to segregate the antitumor effects by potential off-tumor toxicities." (PMID 37993874, 2023). "Inhibition of CSPG4 by gene deletion or treatment with anti-CSPG4 antibodies inhibits tumor growth in xenografts from some malignancies." (PMID 36221119, 2022). "In our study we evaluated the CSPG4 expressions for having an idea of the pericytic density in the tumor tissue." (PMID 36422502, 2022). "By contrast, 84 sites were differentially methylated between both tumor groups, calling for further investigations in order to assess an eventual functional link with CSPG4." (PMID 36221119, 2022). "Upon treatment with decitabine-dosing very similar to that used in the present study, CSPG4 upregulation was demonstrated in tumor cells that lost CSPG4 expression." (PMID 36291817, 2022). "We interpret this observation as a possible immune escape mechanism in more aggressive lesions where subjects whose adaptive immune system generated antibodies to CSPG4 lead to an evolutionary tumor response to downregulate this receptor." (PMID 36110930, 2022). "CSPG4, a cell surface proteoglycan, displays overexpression in certain human cancers, low expression in normal tissues, and roles in tumor growth and dissemination." (PMID 35267618, 2022). "In multivariate analysis, the “CSPG4-high” group (HR=3.47, 95% CI 1.73–6.95, p=4.59E−04) and higher pathological tumor size (HR=1.05, 95% CI 1.01–1.09, p=1.98E−02) remained significant, suggesting independent poor-prognosis value." (PMID 36221119, 2022). "With these in the background, we aimed to investigate the effect of the presence of vessel and pericyte density, and VEGFA and CSPG4 expressions in the tumor tissue, on the efficacy of the bevacizumab in metastatic or recurrent colorectal cancer patients." (PMID 36422502, 2022). "Due to its involvement in tumor progression, CSPG4 is assumed to be less sensitive to antigen-shutdown in response to targeting via CSPG4-specific CAR-T cells." (PMID 36291817, 2022). "High expression of CSPG4 promotes tumor cell proliferation, angiogenesis, immune escape, and therapy resistance." (PMID 35280756, 2022). "For the first time, we show de novo upregulation of CSPG4 in tumor cells with subsequent targeting via CSPG4-specific CAR-T cells." (PMID 36291817, 2022). "CSPG4 guides endothelial tip cells to lead to the tubular structure during the angiogenesis in the direction of hypoxic tumor." (PMID 36422502, 2022). "As a continuous value, the tumor shrinkage was greater in the “CSPG4-low” group than the “CSPG4-high” group (mean −30% vs. −18%, p = 0.159)." (PMID 35267618, 2022). "The "CSPG4-low" tumors displayed profiles suggesting higher anti-tumor cytotoxic immune response and higher potential vulnerability to immune checkpoint inhibitors (ICI)." (PMID 36221119, 2022). "CSPG4 acts as a driver of tumourigenesis by regulating turnover of the extracellular matrix (ECM) to promote tumour cell invasion, migration as well as inflammation and angiogenesis." (PMID 36428658, 2022). "In the current study, we analyzed the expression of HBA, VEGFA, and CSPG4 genes, and meanwhile evaluated the vascular and pericyte density with immunohistochemical analysis of 50 colorectal patients’ tumor tissue." (PMID 36422502, 2022). "As tumor STF2 (CSPG4-high) and STF3 (FAP-high) represent distinct CAF populations, we then performed a coexpression correlation analysis between INHBA expression and the respective cluster markers." (PMID 34642171, 2022).
tumor (continued). "Other significant correlations existed with age, tumor site, and CINSARC risk, the “CSPG4-high" samples being more frequently high-risk according to CINSARC than the “CSPG4-low” samples." (PMID 36221119, 2022). "This was also in line with enhanced activation of the IFNα and IFNγ activation pathways, two cytokines with anti-tumor activity, in “CSPG4-high” tumors (respectively, p = 6.46 × 10−3 and p = 3.23 × 10−3)." (PMID 35267618, 2022). "CSPG4 promotes tumor cell proliferation, angiogenesis, drug resistance, immune escape, and radiation resistance." (PMID 35280756, 2022). "Altogether, these results suggested a higher anti-tumor immune response in “CSPG4-high” tumors than in “CSPG4-low” tumors that relies on both the adaptive and innate immune system." (PMID 35267618, 2022). "We observed dose-dependent increases of CS1 tumor lysis of >80% in CSPG4 CAR T cell treated cells at an E:T ratio of 1:1 versus <5% tumor lysis in the CD19 CAR T cell treated group." (PMID 36110930, 2022). "Of note, the Th1 immune cell type was not significantly different between the two tumor groups, suggesting that, even though the immune infiltrate was higher in “CSPG4-high” tumors, there is still room to increase anti-tumor immune response efficiency." (PMID 35267618, 2022). "In aggregate, the benefits of generating targetability for CSPG4-CAR-T cells via decitabine treatment clearly outweighs conceivable CSPG4-mediated tumor progress promoting actions." (PMID 36291817, 2022). "In sum, CSPG4 fosters crucial steps in tumor progression, thereby possibly conferring growth advantages on CSPG4-positive tumor cells." (PMID 36291817, 2022). "In vivo, the CSPG4-CAR.CIKs delayed or reversed the tumor growth in three STS xenograft models (leiomyosarcoma, undifferentiated pleomorphic sarcoma, and fibrosarcoma)." (PMID 36221119, 2022). "By contrast, the "CSPG4-high" tumors displayed profiles implying an immune-excluded tumor microenvironment, potentially induced by hypoxia, resulting from an immature chaotic microvasculature, and/or the presence of contractile myofibroblasts." (PMID 36221119, 2022). "When M14 cells were transfected to express CSPG4 antigen on its extracellular surface, a >30-fold increase in tumor lysis was observed in CSPG4-transfected M14 cells when treated with CSPG4 CAR T cells at a 1:1 E:T ratio." (PMID 36110930, 2022). "CSPG4/NG2 does not have to be localised to cell membranes to produce an effect on angiogenesis, as soluble CSPG4/NG2 released from tumour cells has also been shown play an important role in development and pathogenesis." (PMID 36428658, 2022). "The binding of the conjugated antibodies via the Fab region to the target antigen CSPG4 on tumor cells was evaluated by flow cytometry and immunofluorescence microscopy." (PMID 34513315, 2021). "It has been widely described that CSPG4 has a key role in several oncogenic pathways required for malignant progression and metastatization and is overexpressed by tumor cells and CSCs." (PMID 33806296, 2021). "NG2 proteoglycan (also called CSPG4) is supposed to play a relevant role in pericyte proliferation and motility, as well as in pericyte-EC interactions, at the early stages of tumor vascularization in BC." (PMID 34885027, 2021). "On the other hand, deletion of NG2/CSPG4 at tumor initiation activates IGF signaling, a pathway known to positively regulate soft-tissue sarcoma growth." (PMID 34069554, 2021). "Chondroitin sulfate proteoglycan 4 (CSPG4) is a type I transmembrane protein with a central role in tumor progression and metastasis." (PMID 34163465, 2021). "Radiolabeling of anti-CSPG4 IgG/IgE allowed a longitudinal study of the distribution and pharmacokinetics of these antibodies in the mouse tumor model by SPECT imaging." (PMID 34513315, 2021).
tumor (continued). "The tumor uptake of 111In-anti-CSPG4 IgG was clearly visible and reached a plateau of 16–30%ID/g between 24 h and 72 h, the spleen uptake peaked at 67 ± 21%ID/g at 72 h, and liver uptake was relatively constant at 9–11%ID/g between 4 h and 120 h." (PMID 34513315, 2021). "Intracranial delivery of CSPG4 CAR T cells was able to control tumor progression in orthotopic GBM neurosphere xenograft models." (PMID 34113233, 2021). "Gene deletion of this PG or NG2/CSPG4 directed immunotherapy affects tumor behavior depending on the developmental stage." (PMID 34069554, 2021). "CSPG4 is a cell surface PG commonly modified with ofCS that has been exploited as a tumor target in several tumor indications." (PMID 32231047, 2020). "Future experiments will be required to evaluate the efficacy and safety of anti-CSPG4-(PDD) in low-CSPG4 expressing tumor models in vivo." (PMID 32331483, 2020). "This CSPG4-targeted treatment showed target-specific cell killing and a delay in tumor growth in vivo." (PMID 32331483, 2020). "The relationship between NG2/CSPG4 immunoreactivity and overall survival OS was analyzed in two tumor sub-groups, including 18 oligodendroglial tumors (ten grade II and eight grade III) and 24 astrocytic tumors (seven grade II, two grade III, and 15 GBs)." (PMID 32599896, 2020). "Overall, these results provided evidence in support of combining the payload PDD with the anti-CSPG4-IgG1 antibody to generate an ADC with tumor growth-restricting properties in vitro and in vivo in the absence of overt systemic toxicities." (PMID 32331483, 2020). "At present, despite the large amount of preclinical data on the anti-tumor efficacy of CSPG4-targeting therapies, few clinical studies have been reported." (PMID 31769737, 2020). "CSPG4 is known to promote chemotherapy and radiotherapy resistance and, furthermore, play an important role in tumor growth, but is hardly expressed in healthy tissue." (PMID 31936595, 2020). "Here we describe the in vitro and in vivo anti-tumor activity of a novel ADC based on an engineered human/mouse chimeric anti-CSPG4 antibody and a DNA mono-alkylating PDD payload." (PMID 32331483, 2020). "Seeking to curb the potential for on-target/off-tumor toxicity, our group has refined the generation of CSPG4-CAR-T cells via mRNA electroporation." (PMID 31779130, 2019). "Our in vitro studies also excluded the participation of CSPG4 signaling pathways in sensitizing the tumor cells to the combination therapy." (PMID 30625226, 2019). "Mechanistically, CSPG4 expedites the formation of tumor blood vessels by binding and sequestering angiostatin, which is an inhibitor of angiogenesis." (PMID 31779130, 2019). "The promotor of CSPG4 has been shown to be sensitive to methylation, which is reflected by CSPG4 upregulation in several tumor cell lines upon treatment with demethylating agents." (PMID 31195686, 2019). "Another major benefit of CSPG4-CAR-T cells is posed by the capacity to concomitantly target CSPG4-positive TNBC cells and cancer-associated fibroblasts, which assume a crucial role in maintaining the tumor microenvironment." (PMID 31779130, 2019). "Next we investigated the role of CSPG4 internalization to account for the difference in the sensitivity of tumor cells to the 9.2.27-PE38KDEL, ABT combinations." (PMID 30625226, 2019). "The inhibition of CSPG4 signaling diminished AKT and ERK activity, reduced tumor-associated inflammation, decreased the transcription of pro-mitogenic early growth response protein 1 (EGR1), and facilitated the execution of pro-apoptotic programs." (PMID 31779130, 2019). "Concerns about potential on-target/off-tumor toxicity are stirred by CSPG4 presence on smooth muscle cells and pericytes." (PMID 31195686, 2019). "CSPG4, a cell surface proteoglycan, was overexpressed in a huge range of human and animal tumors, the tumor microenvironment, and cancer initiating cells." (PMID 29662647, 2018).
tumor (continued). "There was a lower percentage of Edu-positive cells in tumors lacking Ng2/Cspg4 expression than in controls in both genotypes, showing that Ng2/Cspg4 positively regulates tumor cell proliferation." (PMID 29196603, 2018). "Another important function of NG2/CSPG4 is its role in blood vessel development and its expression in pericytes involved in tumor progression." (PMID 30213051, 2018). "NG2/CSPG4 antibody immunotherapy in human sarcomas established as xenografts in mice similarly decreased tumor volume, and expression of a lentivirus blocking NG2/CSPG4 expression inhibited tumor cell proliferation and increased the latency of engraftment." (PMID 29196603, 2018). "Fisher’s exact test revealed that somatic mutations in CSPG4, DNAH11, INADL and TMPRSS13 were significantly associated with PD-L1-positive expression in RCC tumor cells." (PMID 30349421, 2018). "In ninety-six studied GBs, 50% showed high expression level of NG2/CSPG4 in tumor cells and vessels, together with Nestin and Vimentin, but not with CD133." (PMID 30213051, 2018). "In myeloid-specific and pericyte-specific NG2/CSPG4 null mice, a reduced growth of the tumor was observed." (PMID 30577488, 2018). "Herein, we demonstrate that a DNA-based, synthetic consensus CSPG4 immmunogen induced robust anti-tumor immunity." (PMID 30400835, 2018). "The chondroitin sulfate proteoglycan-4 (CSPG4) is a cell surface proteoglycan overexpressed in a huge range of human and canine neoplastic lesions by tumor cells, tumor microenvironment and cancer initiating cells." (PMID 28668095, 2017). "Naive pericytes, which provide structural support to normal vasculature, express relatively low levels of CSPG4, whereas activated pericytes, mobilized during wound healing and tumor angiogenesis, express higher levels of CSPG4." (PMID 28657611, 2017). "As with other antibody therapeutic applications, CSPG4 has been recognized as a promising candidate for theranostic applications, based on high expression by tumor cells and low expression by healthy cells." (PMID 29375561, 2017). "Taken together, CSPG4 is overexpressed in multiple difficult-to-treat cancers in which it is a prominent player in promoting tumor progression and metastasis via various modes of action." (PMID 28657611, 2017). "The development of anti-cancer therapies directed against CSPG4 represents an unprecedented opportunity to simultaneously target tumor cells, CIC and pericytes on tumor vasculature." (PMID 28668095, 2017). "CSPG4 is expressed at low levels in some normal tissues; therefore, it is important to evaluate and mitigate any on-target, off-tumor toxic effects of CSPG4-specific targeted therapy." (PMID 29375561, 2017). "The mode-of-action of bsAb MCSPxDR5 involved high-affinity binding to tumor cell surface-expressed CSPG4 with concomitant localized enhanced cross-linking of DR5." (PMID 28657611, 2017). "In the context of this review is worth mentioning that a human anti-CSPG4 antibody derivative, scFv-Fc21, has been shown to inhibit tumor growth and migration similarly to its full mAb counterpart." (PMID 28657611, 2017). "Multiple studies demonstrate the importance of a functional full length CSPG4 for the survival, growth, and motility of melanoma tumor cells in vitro and tumor formation in vivo." (PMID 29375561, 2017). "Expression of the CSPG4 rodent homolog has been shown to localize in the invasive front of the filopodia of oligodendrocytes, suggesting involvement in mediating tumor cell motility and cancer dissemination." (PMID 29375561, 2017). "In neoplastic lesions CSPG4 is highly expressed on both malignant cells and activated pericytes within the tumor microenvironment." (PMID 28668095, 2017). "The relationship between normal CSPG4 expression and tumor-related overexpression will be discussed in the following section." (PMID 28657611, 2017). "CSPG4 has been reported to exhibit a role in the growth and survival as well as in the spreading and metastasis of tumor cells." (PMID 29375561, 2017).